CD40 (CD40 molecule)
Diseases named in the same sentence as CD40 in open-access papers (continued):
Sharing a sentence is not in itself a finding about the gene and the disease.
melanoma (continued). "A case report of a patient with melanoma that attained completed remission following anti-CD40 treatment demonstrated the expansion of a de novo TCR repertoire identified years after completion of the therapy suggesting a durable impact on the immune response." (PMID 36230990, 2022). "Agonistic anti-murine TNF receptor such as CP-870893, a fully human anti-CD40 monoclonal antibody, has been assessed in clinical trials with beneficial efficacy in melanoma and pancreatic cancers." (PMID 35585567, 2022). "Our study suggests that activated B cells or CD40-positive B cells are crucial to enhance anti-melanoma immunity." (PMID 35720386, 2022). "CD40 is abnormally highly expressed in epithelial tumors such as lung, colorectal, breast, ovarian, and melanoma, while its expression is lower in normal tissues." (PMID 36675706, 2022). "Recently, our group demonstrated that RAS/RAF/PI3K pathway inhibition promotes ICD and augments response to immune checkpoint blockade (ICB), which mechanistically relies on CD40 induction by melanoma cells." (PMID 34758832, 2021). "CD40 agonistic antibodies demonstrated encouraging efficacy in melanoma, pancreatic carcinoma and lymphoma in early clinical trials 26-28." (PMID 33408788, 2021). "We also find that the levels of CD40 in human melanoma cells correlate to the response to RAF inhibitor and ICB treatments." (PMID 34092233, 2021). "The RGS-initiated tumor suppression was partially reversed by either knockdown of CD40 expression in melanoma cells or depletion of CD8+ cytotoxic T cells." (PMID 34092233, 2021). "RGS-induced tumor growth inhibition depends on CD40 upregulation in melanoma cells followed by immunogenic cell death, leading to enriched dendritic cells and activated T cells in the tumor microenvironment." (PMID 34092233, 2021). "This study provides proof of concept that the inhibition of RAS/RAF/PI3K-pathway induces CD40 upregulation and immunogenic cell death in melanoma cells, which sensitizes them to ICB therapy." (PMID 34092233, 2021). "In vitro stimulation in malignant melanomas as well as intratumoral activation of CD40 in melanoma in mouse models have shown promising results." (PMID 34368282, 2021). "Together, these data suggest that CD40 is induced in tumor cells of melanoma patients responding to the therapies targeting RAS/RAF/MEK pathway." (PMID 34092233, 2021). "Here, we identified that the death rate of CD40+ melanoma cells was 3-fold higher than in CD40− melanoma cells for both RGS-treated YUMM3.3 and B16F10 models." (PMID 34092233, 2021). "While the CD40 level does not correlate with the drug sensitivity to RAF inhibitors for all cancer types, human melanoma cells with increased CD40 at either copy number or mRNA levels are significantly more sensitive to the RAF inhibitor treatments." (PMID 34092233, 2021). "In melanoma models, macrophages activated in vivo by CD40 ligation using an anti-CD40 monoclonal antibody and co-cultured with B16 melanoma cells exhibited tumoristatic activity." (PMID 34831416, 2021). "We demonstrate here that RGS and BRAF/MEK inhibitors induce CD40 expression on murine melanoma cell lines and responsive patient melanoma cells in PDX models." (PMID 34092233, 2021). "High CD40 expression level correlates with beneficial T-cell responses and better survival in a TCGA dataset from melanoma patients." (PMID 34092233, 2021). "The prevalence of reduced CD40 expression in tumor versus normal tissue was identified in many cancer types, including melanoma." (PMID 34758832, 2021). "Applying a cutoff Spearman correlation rho of ≥ 0.3 and an adjusted p-value of <0.001, we found that 198 genes in ccRCC, 361 genes in melanoma, and 935 genes in pancreatic adenocarcinoma were correlated with CD40 gene expression." (PMID 33804039, 2021).
melanoma (continued). "The prediction performances of CD40 are comparable to CD8 in ≥50% melanoma cohorts and one gastric cancer cohort, where both biomarkers exhibited an AUC > 0.7, predicting a strong likelihood of positive response to immunotherapy." (PMID 34758832, 2021). "We have shown that human melanoma cells can induce both B cell receptor and CD40 signaling in activated B cells." (PMID 34359321, 2021). "Here, we investigated the role of focused ultrasound based boiling histotripsy (HT) and in-situ anti-CD40 agonist antibody (αCD40) combinatorial therapy in enhancing therapeutic efficacy against ICI refractory murine melanoma." (PMID 33391491, 2021). "Together, our work reveals a novel role of RAS/RAF/PI3K inhibition in ICD via promoting CD40 expression on melanoma cells as well as in inducing an anti-tumor immune response." (PMID 34092233, 2021). "To further dissect the prognostic value of melanoma cell-intrinsic CD40 to ICB, we retrieved and analyzed the single cell (sc) RNA-Seq dataset of melanoma patients from Single Cell Portal (Broad Institute)." (PMID 34092233, 2021). "Treatment with either dabrafenib and trametinib or with RGS, increased CD40+SOX10+ melanoma cells in the tumors of melanoma patients and patient-derived xenografts." (PMID 34092233, 2021). "RAS/RAF/PI3K inhibition promotes CD40 expression by melanoma cells, induces immunogenic cell death, and enhances response to immune checkpoint inhibitors." (PMID 34092233, 2021). "The number of CD40+SOX10+ melanoma cells increased to 103 post BRAF treatment in the one tumor that did not have CD40+SOX10+ cells prior to BRAF inhibitor treatment." (PMID 34092233, 2021). "Several CD40 correlating genes that were shared between pancreatic adenocarcinoma and melanoma are involved in antigen presentation including TAP1, TAP2, HLA-DPB2, and HLA-DR85." (PMID 33804039, 2021). "As expected, we observed CD40+SOX10+ melanoma cells in the TME of all 11 post-treatment samples and in 10 of 11 pretreatment samples." (PMID 34092233, 2021). "In melanoma, CD40 is generally expressed by 30–50% human melanocytic lesions and melanoma cell lines." (PMID 34092233, 2021). "Proinflammatory cytokines, such as interferon-gamma (IFNγ) and tumor necrosis factor-alpha (TNFα), and epigenetic modulators, such as histone deacetylase (HDAC) inhibitors, can induce CD40 expression on melanoma cells." (PMID 34092233, 2021). "A reduced CD40 expression was observed in NRASwt/BRAFmut melanoma compared to NRASwt/BRAFmut nevus tissues." (PMID 34758832, 2021). "We isolated tumor endothelial cells from B16-F10 melanoma treated with either agonistic CD40 mAb (FGK4.5) or isotype control and generated genome-wide transcriptome data by RNA-sequencing." (PMID 32231867, 2020). "Hoves and colleagues provided evidence a beneficial loss of TAMs by applying a combination therapy of inhibitory α-CSF-R and agonistic α-CD40 to melanoma mice." (PMID 32470095, 2020). "Here, we have investigated how tumor endothelial cells transcriptionally respond to CD40-stimulating immunotherapy by isolating tumor endothelial cells from agonistic CD40 mAb- or isotype-treated mice bearing B16-F10 melanoma, and performing RNA-sequencing." (PMID 32231867, 2020). "CD40 agonists, which activate both B cells and DCs, showed remarkable clinical benefits in melanoma patients when combined with checkpoint inhibitors." (PMID 33505304, 2020). "Incubation of primary human monocytes (HuMo) with sEVs derived from A375 melanoma cells decreased the expression of co-receptor protein CD40 and HLA-DR, while the mean fluorescence intensity of HLA-ABC molecules and CD86 remained largely unchanged." (PMID 31269655, 2019). "CP-870,893 (Pfizer/VLST), a strong agonist of CD40, is a fully human IgG2 with well-proved antitumor immunity in patients with solid tumors, including melanoma and pancreatic cancer." (PMID 28660349, 2018).
melanoma (continued). "Several clinical trials in which agonistic anti-CD40 Ab is tested for its effect in solid tumors such as melanoma, non-small cell lung cancer and pancreatic duct adenocarcinoma sometimes in combination with checkpoint inhibitors have been started." (PMID 30237798, 2018). "Consequently, we find high numbers of intratumoral CD8+ T-lymphocytes after treatment with anti-CD40 antibodies in combination with sunitinib, associated with a significant reduction in tumor growth and increased survival of mice bearing either B16.F10 melanoma or T241 fibrosarcoma." (PMID 27385210, 2016). "Here, we have investigated the potential benefit of combining agonistic anti-CD40 antibody therapy with sunitinib treatment in B16.F10 melanoma and T241 fibrosarcoma." (PMID 27385210, 2016). "A 27.3% response rate was obtained with anti-CD40 (CP-870893) plus anti-CTLA-4 (tremelimumab) in a phase I study in melanoma patients (NCT01103635)." (PMID 27847783, 2016). "CD40 targeted viruses have subsequently been used in pre-clinical studies for the treatment of prostate and cervix cancer as well as melanoma." (PMID 25933160, 2015). "Subsequent research showed CD40 expression on cancer cells of the breast, ovary, intestines, liver, glioma, nasopharynx, melanoma, or lymphoma." (PMID 25117071, 2014). "This is in contrast with what has been found by others, e.g., co-administration of IMQ and anti-CD40 is ineffective against intradermal B16 melanomas, and required a combination of TLR3, TLR4 and TLR7 stimulation to produce 50% tumor rejection." (PMID 25518732, 2014). "A synthetic TRP2180–188 peptide vaccine was recently combined with several toll-like receptor agonists and an anti-CD40 antibody to induce potent CD8+ T cells with therapeutic tumor efficacy against established B16 melanoma." (PMID 21318177, 2010). "CP-870,893 is a fully human, selective agonist CD40 mAb and has shown early clinical promise in phase I trials, particularly in patients with advanced melanoma." (PMID 19906293, 2009). "A more recent analysis of combined vs. monotherapy in a mouse melanoma model showed that combined activation via CD40 and TLR9 results in tumor-infiltrating CD8+ T cells at a very high frequency and with potent anti-tumor activity." (PMID 19906293, 2009). "HDACi treatment enhanced the expression of MHC class II, CD40 and B7-1/2 on B16 cells and vaccination with HDACi-treated melanoma cells elicited tumor specific immunity in both prevention and treatment models." (PMID 18070359, 2007). "CD40 is expressed not only on cells of the hematopoietic system but also on melanoma and on epithelial cells, in particular breast, lung, or ovarian carcinoma cell lines." (PMID 16545138, 2006). "Treatment with CD40 agonist antibody, which promotes differentiation of monocytes and macrophages towards a proinflammatory phenotype, reduced tumor growth and improved survival in B2m-null melanoma and colorectal cancer models." (PMID 41676732, 2026). "Thus, preventing the reprogramming of macrophages induced by inhibition of CD40/IL-27 signals shows potential as a precise immunotherapeutic strategy in melanoma.As specific components of myeloid origin, platelets can also affect macrophage polarization." (PMID 40453088, 2025). "In clinical trials, CD40 agonists have demonstrated tolerable safety profiles, with some showing partial responses and disease stabilization in patients with pancreatic cancer, melanoma, and non-small cell lung cancer (NSCLC)." (PMID 40821795, 2025). "Similarly, CD40 agonist sotigalimab nanoparticles induced durable remission exceeding 26 months in 15.2% of PD-1 inhibitor-resistant melanoma patients." (PMID 40933890, 2025). "CD40 has long been shown to be expressed in melanoma (and later)." (PMID 40647495, 2025).
melanoma (continued). "As previously reported, agonistic anti-CD40 monoclonal antibodies effectively suppressed melanoma growth, which was accompanied with a strong induction of expression of anti-tumorigenic genes, but reduced levels of genes related to pro-tumorigenic and tissue-repairing processes in TAMs." (PMID 36823405, 2023). "However, a recent in vivo study showed the effective, neutrophil-mediated killing of B16 melanoma cells when combining an IgG antibody targeting gp75 (a protein expressed on B16 melanoma cells), an CD40 antagonist and TNF." (PMID 37566060, 2023). "CD40 is a target of significant interest in many solid cancers, including melanoma." (PMID 36211808, 2022). "Furthermore, CD40-positive B cells were required to generate optimal anti-melanoma immunity in response to the combination therapy." (PMID 35720386, 2022). "Analysis of TCGA data of CD40 expression in pancreatic adenocarcinoma, melanoma and RCC demonstrated a strong correlation with Ag presentation molecules, TLRs and T cell function supporting the use of CD40 agonists as an attractive cancer immune therapy for DC activation." (PMID 36230990, 2022). "A phase I trial, which enrolled 26 patients with anti-PD-1/PD-L1-resistant melanoma (n = 12), non-small cell lung cancer (n = 1) and renal cell carcinoma (n = 13), evaluated the safety of the CD40 agonist APX005M (sotigalimab) and CSF1R inhibitor (cabiralizumab) with or without nivolumab." (PMID 35742834, 2022). "Next, we determined whether only CD40-positive B cells play an essential role in anti-melanoma immunity." (PMID 35720386, 2022). "Given that RGS treatment in mice increased CD40, CD80, and ICOS-L expression levels on tumor cells, and this was associated with a better therapeutic outcome, we questioned whether the levels of CD40/CD80/ICOS-L have any prognostic value in melanoma patients." (PMID 34092233, 2021). "While the loss of CD40 copy number is very rare in melanoma patients (~ 1.25%, TCGA), ~ 50% of melanoma patients exhibit CD40 copy number gains and thus may be prone to exhibit enhanced inducible expression of CD40." (PMID 34092233, 2021). "Notably, CD40 expression in a patient’s melanoma cells significantly and negatively correlates with the resistance level to ICB immunotherapy." (PMID 34092233, 2021). "Consistently, a correlation matrix profiling of gene mRNA expression in TCGA collection of melanoma tumors showed that CD40 expression significantly and positively correlates with CD4 and CD8 infiltrates, as well as with type 1 cytokine responses based on IFNγ and GzmB expression patterns." (PMID 34092233, 2021). "Thus, we further validated the CD40 expression in nevus samples and compared it to expression in melanoma tissues using the NCBI-GSE112509 bulk RNA-Seq dataset." (PMID 34758832, 2021). "Also, human melanoma cells with increased CD40 at either copy number or mRNA expression levels are significantly more sensitive to the RAF inhibitor treatments." (PMID 34758832, 2021). "However, the regulation and function of CD40 in melanoma cells and its prognostic value in treatment responses remain to be examined." (PMID 34092233, 2021). "Notably, we observe a significant induction of CD40+SOX10+ melanoma cells in the tumors of melanoma patients post BRAF inhibitor treatment by multiplex IHC analysis." (PMID 34092233, 2021). "To explore whether RAS and RAS- mediator expression levels correlate with CD40 expression in a patient’s melanoma cells, we further screened the mRNA expression profile of genes in the N-RAS regulation pathway microarray (Bio-Rad)." (PMID 34092233, 2021). "Moreover, CD40 is a potential predictive biomarker of response to ICB therapy for some tumor types (melanoma, gastric cancer, and glioblastoma)." (PMID 34758832, 2021). "We identified a gain of CD40 copy number (CD40-gain) in 177 out of 358 TCGA-melanoma patients." (PMID 34092233, 2021).
melanoma (continued). "Furthermore, CD40 was shown to co-stimulate both anti-CD3-triggered CD4+ and CD8+ human T cells and enhance melanoma cell susceptibility to T cell lysis." (PMID 34092233, 2021). "Furthermore, NRASmut melanoma exhibited a reduced CD40 expression compared to either NRASwt/BRAFwt nevi, NRASwt/BRAFmut nevi or NRASwt/BRAFwt melanoma tissues." (PMID 34758832, 2021). "Indeed, intratumoral CD40 activation in combination with ICB induces T cell-mediated eradication of melanoma in animal models." (PMID 34092233, 2021). "The CD40KD melanoma cells were resistant to IFNγ-mediated induction of CD40 expression." (PMID 34092233, 2021). "We determined that the mean frequency of CD40 positive melanoma cells in these patients is 10.54%." (PMID 34092233, 2021). "While both antigen-presenting cells (APCs, including DCs, macrophages and B cells) and melanoma cells were reported to express CD40, subsequent tSNE analysis by flow cytometry showed that in our experimental setting RGS treatment-induced CD40 expression on CD45− cells but not on APCs." (PMID 34092233, 2021). "Also, on human myeloid-derived dendritic cells, anti-CD40-CD40L-melanoma gp100 peptide induced more sustained Class I antigen presentation compared to anti-CD40-gp100 peptide." (PMID 35095862, 2021). "ccRCC and melanoma shared three genes that correlate to CD40 (OASL, GNLY, and IFI35)." (PMID 33804039, 2021). "Given that RGS interferes with RAS-RAF activation and triggers CD40-dependent anti-tumor effects in melanoma, we questioned whether the CD40 level is prognostic of response to previously used effective therapy, such as RAF inhibitor treatment." (PMID 34092233, 2021). "Antitumor activity of the agonist CD40 antibodies has been observed in patients with melanoma." (PMID 32797726, 2020). "Notably, expression of IDO1 in tumor infiltrating leukocytes was considerably lower than that observed in tumor endothelial cells from agonistic CD40 mAb treated B16-F10 melanomas." (PMID 32231867, 2020). "The anti-CD40 antibody was proved to activate tumor TAMs and block tumor growth in mice and human models of pancreatic carcinoma, in a mice glioma model, and in a mice model of melanoma." (PMID 28660349, 2018). "Similarly, CpG-ODN was also investigated in combination with an agonistic CD40 antibody in established tumours of B16 melanoma and 9464D neuroblastoma mouse models." (PMID 30577495, 2018). "Nevertheless, the LRP analyses detected IDO1, LAG3, TIM-3, VISTA, and CD40 in the 22 melanomas." (PMID 28546465, 2017). "Further studies using CD40 stimulation in malignant melanoma are warranted." (PMID 28427434, 2017). "Indeed, anti-CD40 (APX005M) is currently studied in combination with anti-PD-1 (pembrolizumab) in a phase I/II trial in melanoma patients (NCT02706353)." (PMID 27847783, 2016). "Antibody targeting of VEGF/VEGFR2 signaling increases the efficacy of adoptive T-cell therapy of established B16 melanomas and has been demonstrated to enhance the antitumor effect of agonistic CD40-antibodies after subcutaneous injection of RM-1 prostate cancer cells." (PMID 27385210, 2016). "Here, we show that combining agonistic CD40 monoclonal antibody (mAb) therapy with vascular targeting using the tyrosine kinase inhibitor sunitinib decreased tumor growth and improved survival in B16.F10 melanoma and T241 fibrosarcoma." (PMID 27385210, 2016). "As a follow up study to those that indicated that the synergistic effects of anti-CD40 and CpG increase classical activation, a combination of anti-CD40, CpG, and the chemotherapeutic agent cyclophosphamide was used to study treatment of melanoma in vivo." (PMID 26932379, 2014). "Moreover, the administration of anti-CD40 antibodies has been observed to activate macrophages, thus enabling them to inhibit proliferation of melanoma B-16 cells and to stimulate them to interferon production." (PMID 25117071, 2014).